IL37 (interleukin 37)
Diseases named in the same sentence as IL37 in open-access papers (continued):
Sharing a sentence is not in itself a finding about the gene and the disease.
tumor (continued). "In melanoma, high levels of IL-37 expressed by peripheral Tregs were found to mirror the secretion of IL-1β mediators, especially TGFβ, by the tumor, suggesting it could be used as a possible biomarker for tumor-induced immunosuppression." (PMID 36551790, 2022). "Thus, DCs were responsible for IL-37-induced anti-tumor immunity in HCC, which might help develop novel cancer immunotherapeutic approaches." (PMID 35619702, 2022). "Therefore, intracellular mature IL-37 may be considered as a potential therapeutic agent against Rac1 activity and consequent tumor progression." (PMID 34248996, 2021). "Hence, they concluded that IL-37 might be a potent and novel tumour suppressor in patients with NSCLC." (PMID 34336101, 2021). "IL-37 is not only an inflammatory inhibitor but also an inhibitor of inherent inflammatory and immune responses, and it may play a role in inhibiting tumor growth in the tumor microenvironment." (PMID 33489865, 2020). "Given that tumor growth and metastasis depends on angiogenesis, the ability of IL-37 to promote the formation of new blood vessels in hypoxia regions of tumors could represent an important pro-tumorigenic function for IL-37." (PMID 31231372, 2019). "It remains unclear whether IL-37 has direct tumor suppressing properties." (PMID 31781119, 2019). "Further investigation of the effects of IgE antibodies on the expression of additional soluble mediators such as IL-17A, and other family members, and IL-37, reported to influence macrophage phenotype, may shed light into the impact of IgE-FcεRs interactions in the tumour microenvironment." (PMID 30956175, 2019). "Moreover, given that IL-37 suppresses inflammatory cytokine production, IL-37 could potentially alter the tumor microenvironment in favor of one that promotes tumor rejection." (PMID 31231372, 2019). "IL-37 may change tumor microenvironment in vivo, so as to play its antitumor effect." (PMID 29805973, 2018). "Thus, IL‐37 may inhibit tumor angiogenesis through recruiting neutrophils, which needs further exploration." (PMID 30004182, 2018). "Thus, the mechanisms of anti-tumor effects of IL-37 need further studies." (PMID 28467774, 2017). "Thus, the high IL-37 level in cancer adjacent tissues might have the immune suppression effects and the low expression in the tumor tissue might have the tumor promotion effects." (PMID 28467774, 2017). "Further analysis showed that the lack of IL-37 tightly associated with cancer metastasis and poor survival, and could be developed as novel prognostic marker to predict tumor recurrence." (PMID 28467774, 2017). "Therefore, inside of the tumor cells, IL-37 might suppress some factors which contribute to tumor development, such IL-6 or β-catenin we discussed here." (PMID 28467774, 2017). "Therefore, IL-37 could function not only as a fundamental inhibitor of innate immunity, but also as a novel tumor suppressor in HCC." (PMID 27835881, 2016). "Despite this knowledge, the biological role of IL-37 in tumor development remains largely unknown." (PMID 26791086, 2016). "IL-37 suppresses many pro-inflammatory pathways, including NF-κB, MAPK, and the cytokines IL-1β, IL-6, and TNF, thereby inhibiting tumor growth." (PMID 41596472, 2026). "IL-37 exerts direct anti-inflammatory action and blocks nuclear factor kappa B (NF-κB) and mitogen-activated protein kinase (MAPK), reducing tumor growth, angiogenesis, and metastasis." (PMID 41596472, 2026). "IL-37 was measured at the time of clinical assessment, and routine laboratory parameters, disease severity scores (MELD, Child-Pugh), and tumour staging (BCLC, LI-RADS) were recorded." (PMID 42073372, 2026). "The diminished tumour size correlated with a decrease in VEGF and subsequent neovascularization in the tumours of recipients receiving IL-37-transfected cells." (PMID 40191189, 2025). "It is possible that intra-tumoral IL-37 in NSCLC is primarily intracellular and pro-inflammatory, thereby inhibiting tumour growth." (PMID 40191189, 2025).
tumor (continued). "Further studies revealed IL37 facilitated OSCC progression via promoting macrophage polarization from M1 to M2 and enhancing tumour cell proliferation." (PMID 39500733, 2024). "Furthermore, in an HCC transplantation model in vivo, the inoculation of IL-37-transfected TAMs into recipients resulted in a substantial reduction in tumour growth compared to mice without IL-37 transfection, providing additional confirmation of the anti-tumour function of IL-37." (PMID 38312834, 2024). "This research holds promise for understanding the potential role of IL37 in OSCC and its impact on macrophage‐mediated immune responses in the context of tumour progression." (PMID 39500733, 2024). "The findings of this study indicate that IL37 accelerates OSCC progression through promoting M2 macrophage polarization and tumour cell proliferation." (PMID 39500733, 2024). "clarified that IL-37 concentration in NSCLC patients’ plasma was obviously decreased, and its downregulation was closely related to the advanced Tumor Node Metastasis (TNM) stage." (PMID 37928545, 2023). "IL-37 serum concentration in RCC patients was decreased compared to that in healthy controls, and was negatively correlated with tumor size as well as stage." (PMID 37928545, 2023). "Further results supplied that IL-37 induced autophagy and apoptosis by inhibiting PI3K/AKT/mTOR signaling pathway in HCC cells (SMMC-7721 and Huh-7), thereby suppressing tumor growth." (PMID 37928545, 2023). "It is reasonable to suppose that IL-37 can reduce the exhaustion of immune cells in the TME and promote the anti-tumor response by downregulating the expression of PD-1 and TIM-3 protein on other immune cells surface." (PMID 37928545, 2023). "Our findings on the interaction of IL‐37 and CD103+DCs in the tumor microenvironment will help to develop new strategies for cancer treatment strategies." (PMID 36891351, 2023). "IL-37 was also found to downregulate the expression of TIM3 on canonical NK cells, which plays a vital role in the anti-tumor immune response by inhibiting the immune suppression mediated by Treg." (PMID 36237303, 2022). "The first aim of this study was to investigate the expression patterns of IL-37 and its receptor, SIGIRR, in tumor biopsies of various human cancer types, utilizing the Tissue Atlas tool of the Human Protein Atlas database." (PMID 36551790, 2022). "Reduced colonic IL-37 and IL-38 is relating to CRC invasion and distant metastasis, suggesting a protective role for IL-38 within the tumor micro-environment." (PMID 35186997, 2022). "IL-37 was reported to suppress the activation of NF-κB and MAPK, and negatively regulate proinflammatory cytokines and pro-tumor signaling pathways." (PMID 36237303, 2022). "Of the six genes (IGF2BP1, GPRC6A, IL37, CRCT1, SEMG1, and PSG7) for which we analyzed the differential expression between tumor tissues and healthy tissues in TCGA, four genes (CRCT1, PSG7, IL37, and IGF2BP1) showed notable differences." (PMID 36276966, 2022). "When compared tumor volume with SW1990/pLV-Vector cells, the tumor volume of SW1990/pLV-IL37 cells became smaller, suggesting the suppression of IL-37 on PDAC cells (P < 0.05)." (PMID 32226541, 2020). "Compared with control group, expression level of IL-37 in HCC group was decreased and inversely proportional to tumor size." (PMID 29805973, 2018). "In the meantime, we found IL-37-over-expressing tumors had decreased CD34 level, which suggested an inhibited tumor angiogenesis." (PMID 26791086, 2016). "On univariate survival analysis revealed histologic grade (P=0.009), tumor staging (BCLC) (P=0.033), microvascular invasion (P=0.030), and IL-37 expression (P=0.013) as significant variables for OS." (PMID 27835881, 2016). "The results derived from in vitro cell proliferation, colony formation and in vivo tumor progression assays confirmed that overexpression of IL-37b suppresses the potency of HCC cell growth and proliferation, which were reversed upon IL-37 knockdown." (PMID 27835881, 2016).
tumor (continued). "In conclusion, we provide evidence for the first time that IL-37 was decreased in human NSCLC and inhibits lung tumorigenesis in vivo, possibly by inhibiting tumor angiogenesis." (PMID 26791086, 2016). "Univariate analysis indicated that tumor size (P=0.023), histologic grade (P=0.005), tumor staging (BCLC) (P=0.017), microvascular invasion (P=0.009) and IL-37 expression levels (P=0.009) reached significance for DFS." (PMID 27835881, 2016). "In this study we found IL-37 expression was down-regulated in human HCC tissues and cell lines, and was negatively correlated with tumor size, vascular invasion, as well as overall-survial and disease-free survival (OS and DFS) of HCC." (PMID 27835881, 2016). "In this sense, IL-37 is expressed at lower levels in the tumor tissues of patients with NSCLC, and it correlates with poorer overall survival compared to patients with high IL-37 expression." (PMID 27445423, 2016). "Patients with prevalent HCC exhibited numerically lower IL-37 compared with those who developed HCC during follow-up, suggesting that IL-37 decline may precede overt tumour manifestation." (PMID 42073372, 2026). "It is worth noting that the absence of infiltrating leukocytes in the inoculated tumours among recipients with IL-37 transgenic and non-transgenic cancer cells." (PMID 40191189, 2025). "However, IL-37 protection is demonstrated in an IL-37 transfected HCC animal model, showing significantly reduced tumour size." (PMID 38312834, 2024). "Importantly, both the levels of IL-37 and SIGIRR were found to correlate with the stage of the BLCA tumor, with lower expression detected in advanced stages." (PMID 37298214, 2023). "Given the results found in mice, we examined whether IL‐37 weakened the ability of CD103+DCs to prime CD8+ T cells in vitro, thus inhibiting the anti‐tumor immunity." (PMID 36891351, 2023). "However, when the whole tumor (including TME) was analyzed, IL-37e was found to be primarily expressed and, indeed, at dramatically greater levels compared to (a) other IL-37 isoforms and (b) IL-37e expressed by BLCA cell lines." (PMID 37298214, 2023). "The enhancement of IL-37 expression by HCC cells is accompanied by an increase in the levels of CCL3 (chemokine (C-C motif) ligand 3) and CCL20, which further promotes the recruitment of CD1a+ dendritic cells (DCs) in the tumor infiltrate." (PMID 37298214, 2023). "In our study, the results displayed that IL‐37 did not affect NK cells and Mø in tumor‐bearing skin tissues and SDLN, whereas a decrease in DCs was always detected in IL‐37tg mice, which was consistent with previous reports." (PMID 36891351, 2023). "Based on cumulative data from recent years, IL-37 employs its tumor-regulatory effects to control the functions of other immune and non-immune components of the tumor microenvironment (TME)." (PMID 37298214, 2023). "In assays in HCC Hep3B cells in vitro and HCC mouse model constructed of Hepa1-6 cells in vivo, transduced IL-37 was also verified to enhance local infiltration of CD57+NK cells that expresses IL-18Rα and IL-1R8 chains in tumor sites to suppress tumorigenicity." (PMID 37928545, 2023). "Although the exact cellular sources and targets of IL-37 have not been identified in BLCA TME, we attempted to explore whether genetic and/or expression alterations of IL-37 and SIGIRR affect the involvement of various cell types infiltrating the tumor." (PMID 37298214, 2023). "Some factors in the TME could modify the function of tumor-infiltrating DCs, such as the liver X receptor (LXR), IL-37 and alpha-fetoprotein (AFP)." (PMID 35619702, 2022). "Moreover, IL-37 indirectly upregulated the expressions of MHC class II molecules, CD86 and CD40, on DCs and, in turn, increased T-cell-mediated anti-tumor immunity by inducing DCs to producing cytokines." (PMID 35619702, 2022).
tumor (continued). "Focusing on the pivotal role of the tumor-immune microenvironment in LUAD development and progression, we aimed at the exploration of the expression patterns of IL-37, a novel cytokine with regulatory properties in LUAD tumors, using various bioinformatics tools and available databases." (PMID 36551790, 2022). "Exploration through the “Gene” module of the TIMER2.0 webserver revealed that IL37 gene expression levels, as assessed in previous RNAseq experiments, were linearly correlated with certain immune cell populations infiltrating the LUAD tumor." (PMID 36551790, 2022). "Other studies reported that IL-37, LECT2, and TNFSF15 suppress tumor growth." (PMID 35563525, 2022). "Moreover, DCs treated with IL-37 are stimulated to secrete IL-2, IL-12, IL-12p70, IFN-α and IFN-γ, which indirectly enhance the anti-tumor effect of T lymphocytes." (PMID 34248996, 2021). "Moreover, intratumoral IL-37 expression was positively correlated with infiltrating CD57+ NK cells, and higher IL-37 expression predicted smaller tumor size and better survival for HCC patients." (PMID 33262461, 2021). "Indeed, intracellular mature IL-37 binds to the CAAX motif in the C-terminal hypervariable region of Rac1, which is normally involved in tumor angiogenesis and metastasis." (PMID 34248996, 2021). "In conclusion, our research uncovered IL-37/STAT3/HIF-1α negative feedback signaling drives tumor development and Gem resistance in PDAC." (PMID 32226541, 2020). "Moreover, overexpression of IL-37 by hepatic tumor cells resulted in enhanced local CD57+ NK cell infiltration of the tumors and suppressed tumor growth in vivo." (PMID 31231372, 2019). "Additional mechanisms proposed for the anti-metastatic function include inhibition of Rac1 activation, with the intracellular mature form of IL-37, but not its extracellular form, markedly inhibiting the migration of multiple tumor types." (PMID 31231372, 2019). "Also, IL‐37‐over‐expressing tumors had decreased CD34 level, which suggested an inhibited tumor angiogenesis." (PMID 30004182, 2018). "To explore the inflammatory stimuli from CTCs that stimulate G-CSF and IL-6 expression, we focused on the tumor cell-derived TLR2 and TLR4 (TLR2/4) ligands, since IL-37 could suppress TLR4 ligand-induced inflammatory response." (PMID 28415700, 2017). "We found similar cell populations based upon CD11c, CD11b, Gr-1 and DX5 stainings in IL-37- and mock-transfected tumors, suggesting that IL-37 did not affect the anti-tumor immune responses in vivo." (PMID 26791086, 2016). "Furthermore, the decrease in IL37 expression accompanied by MCC950 treatment also resulted in reduced IL1β expression, further verifying that elevated IL37 serves as a self‐protective mechanism for tumour cells against inflammation." (PMID 39500733, 2024). "In conclusion, this mini review makes the case that there are some similarities between IL-37 and IL-38 in inhibiting tumorigenesis of CRC, yet these two interleukins use different signaling pathways in mediating and/or interacting with cancer cells in the tumor microenvironment." (PMID 35186997, 2022). "Specifically, the role of IL-37 for CD8+ CTL tumor immunosurveillance is not well understood." (PMID 35046386, 2022). "To test whether IL-37 is involved in specific immune responses elicited by tumors, we utilized the highly aggressive B16-OVA cancer model which overexpresses the surrogate tumor antigen, ovalbumin (OVA)." (PMID 35046386, 2022). "However, the authors did not measure IL-37 levels within the tumour itself, making comparison to other cancer studies difficult." (PMID 36483045, 2022). "Overexpression of IL-37 failed to change tumor volumes and weights compared to those in controls." (PMID 35046386, 2022).
tumor (continued). "IL-37 mRNA levels were found to be increased by 12-fold in samples from LUAD (n = 524) compared to those from non-LUAD individuals (n = 486, Mann–Whitney p = 3.83 × 10−59), and by 11-fold in tumor compared to paired adjacent normal tissues from LUAD individuals (n = 57; p = 3.81 × 10−8)." (PMID 36551790, 2022). "IL-37 reduces the expression of pro-angiogenic factors and increases the one of antiangiogenic factors in tumor cells, as well as decreases matrix metalloproteinase (MMP) 2 expression in SK-Hep-1 and SMMC-7721 cell lines overexpressing IL-37 and murine tumor models." (PMID 34248996, 2021). "However, we found no change in TILs frequencies in tumors over-expressing IL-37, suggesting that IL-37 did not affect the anti-tumor immune responses in vivo." (PMID 26791086, 2016). "No studies have shown the correlation of IL-37 with tumor angiogenesis in NSCLC." (PMID 26791086, 2016). "Moreover, in the same HCC transplantation model in vivo, inoculating IL-37-transfected TAMs into the recipients resulted in significantly reduced tumour growth compared to mice without IL-37 transfection, providing further confirmation of the anti-tumour function of IL-37." (PMID 38312834, 2024). "Recent findings have demonstrated the role of IL-37 in pancreatic cancers, in which the pancreatic epithelial cells could undergo sustained inflammation-related adaptive response even after inflammation has subsided, accompanied with activated KRAS oncogene to promote tumor development." (PMID 37928545, 2023). "Finally, pathway analysis revealed that IL-37-signaling mediators, such as STAT3, are crucial partners of PD-1, PD-L1, and CTLA-4 pathways, providing hints for an interfering role of this cytokine in the immune-checkpoint blockade of anti-tumor immune responses." (PMID 36551790, 2022). "CD8+ CTLs is poorly infiltration in CRC and indicates poor prognosis, and the negative correlation between tumor infiltrated CD8+ CTLs and IL-37 level were illustrated in CRC." (PMID 35046386, 2022). "In these patients, a negative correlation between IL-37 levels in the serum and CD8+ T cell infiltration in the tumor was also observed." (PMID 36551790, 2022). "From this standpoint, it is altogether remarkable that hepatic expression of IL-37 decreases during HCC evolution and that it does so both in the tumor itself and the non-tumoral tissue adjacent to the tumor." (PMID 31507607, 2019). "Furthermore, IL-37 mediated tumor suppressing ability may be confined to inhibition of tumor proliferation through its action on CD4+ activation without having effects on tumor metastasis." (PMID 29641433, 2018). "Further studies found that IL-37 could directly stimulate the activation and proliferation of CD4+ rather than CD8+ T cells in vitro, and prevent tumor growth in mice." (PMID 37928545, 2023). "Moreover, CTCs failed to induce the tumor-promoting function of neutrophils in B16F1-bearing mice and cir-B16F0-mice, if IL-37 was expressed in vivo." (PMID 28415700, 2017).